HDAC6 (histone deacetylase 6)
Diseases named in the same sentence as HDAC6 in open-access papers (continued):
Sharing a sentence is not in itself a finding about the gene and the disease.
Parkinson disease (30 papers, 2010 to 2025). A progressive degenerative disorder of the central nervous system characterized by loss of dopamine producing neurons in the substantia nigra and the presence of Lewy bodies in the substantia nigra and locus coeruleus. "In this study, the behaviors and Parkinson’s disease-like pathology in HDAC6 deficient mice were analyzed." (PMID 37373121, 2023). "Recent studies have implicated the cytoplasmic histone deacetylase 6 (HDAC6) in several neurodegenerative diseases including Alzheimer’s, Parkinson’s and Huntington’s diseases." (PMID 27535553, 2016). "Therefore, HDAC6 deficiency leads to moderate alterations of behaviors and Parkinson’s disease pathology in mice." (PMID 37373121, 2023). "On this basis, our results suggest that phospho-HDAC6 could be a common hallmark in the formation of intracellular protein aggregates in different forms of parkinsonisms." (PMID 32655357, 2020). "In addition, we propose that HDAC6 could be considered as a common hallmark of parkinsonisms, independently from the nature of protein aggregates (Lewy bodies, Papp–Lantos bodies, and neurofibrillary tangles) and affected cells (neurons and glia)." (PMID 32655357, 2020). "The elevation of HDAC6 expression would lead to the degradation of protein aggregates, which was found in various neurodegenerative disorders, including Alzheimer’s and Parkinson’s diseases." (PMID 39412062, 2024). "Taken together, our results suggest that HDAC6 phosphorylation is specifically involved in pathological and intra-cellular protein aggregation occurring in parkinsonisms." (PMID 32655357, 2020). "Taken together, our findings suggest that both HDAC6 and phospho-HDAC6 regulate the homeostasis of intra-neuronal proteins in parkinsonism." (PMID 32655357, 2020). "In our study we found that selective inhibition of HDAC6 activity by Tubastatin A has protective effects in a rat model of Parkinson’s disease." (PMID 32269243, 2020). "In human, HDAC6 localizes in neuronal Lewy bodies in Parkinson’s disease (PD) and in oligodendrocytic Papp–Lantos bodies in multiple system atrophy (MSA)." (PMID 32655357, 2020). "HDAC6 is the major α-tubulin deacetylase, and its expression is abnormally high in patients with neurodegenerative diseases, including Parkinson’s, amyotrophic lateral sclerosis, and Alzheimer’s, and with cancer and pathological autoimmune responses." (PMID 27997532, 2016). "Consequently, HDAC6 is being explored as a therapeutic target for cancers and various neurodegenerative diseases such as Alzheimer’s disease (AD), Parkinson’s disease (PD), Huntington’s disease (HD), and amyotrophic lateral sclerosis (ALS)." (PMID 39598445, 2024). "Previous evidence has indicated the important role of HDAC6 in tau-mediated neurodegeneration, and HDAC6 may be involved in various neurodegenerative diseases such as AD, Parkinson disease, amyotrophic lateral sclerosis, and Huntington disease." (PMID 38298218, 2024). "Based on previous work indicating that the main tubulin deacetylated enzyme, HDAC6, is present with its active form (i.e. P-HDAC6) in the LBs of different parkinsonism, including PD57, our preferred hypothesis is the increase of Tubulin deacetylation." (PMID 38167511, 2024). "To test whether phosphorylated HDAC6 accumulation in Lewy bodies is restricted to PD, we evaluated the expression of phospho-HDAC6 in other parkinsonisms." (PMID 32655357, 2020). "Thus, our findings reinforce the link between impaired microtubule acetylation in LRRK2 parkinsonism and increased α-tubulin acetylation through inhibiting HDAC6 activity revealed a beneficial effect in mitigating neuronal degeneration in PD." (PMID 33231564, 2020). "Research on HDAC6 is being vigorously pursued for its role in neurodegenerative diseases such as Alzheimer's, Parkinson's, and Huntington's diseases as well as in cancers and use of HDAC6 specific inhibitors has been demonstrated to be beneficial in animal models." (PMID 29201907, 2017).
Parkinson disease (continued). "On the other hand, an induction of HDAC6 would theoretically contribute to the degradation of protein aggregates which characterize various neurodegenerative disorders, including Alzheimer’s, Parkinson’s and Hutington’s diseases." (PMID 23356410, 2013). "Even if the mechanisms by which parkin suppressed parkinsonism remain unclear, parkin participated in the elimination of impaired mitochondria (mitophagy) via the HDAC6-dependent mitochondria ubiquitination." (PMID 23356410, 2013). "Although HDAC6 plays an essential role in aggresome formation and the clearance of misfolded proteins, its sustained overactivation in neurodegenerative settings such as Parkinson’s disease may become detrimental." (PMID 40940748, 2025). "In addition, treatment with HDAC6 inhibitors, which increase acetylation of α-tubulin, reverses transport defects in cellular models of Huntington's disease and LRRK2 mutation-induced Parkinson's disease." (PMID 28105056, 2016). "Histone deacetylase 6 (HDAC6) is involved in the regulation of protein aggregation and neuroinflammation, but its role in Parkinson’s disease (PD) remains controversial." (PMID 37373121, 2023). "Inhibition of HDAC6 attenuates the NLRP3 inflammatory response and protects dopaminergic neurons in experimental models of Parkinson’s disease." (PMID 35910382, 2022). "Moreover, HDAC6 inhibitors reverse axonal transport deficits in mouse models of CMT2F and cellular models of Parkinson's disease and Huntington's disease by increasing acetylated α-tubulin." (PMID 28105056, 2016). "Inhibition or genetic deletion of histone deacetylase 6 (HDAC6), an enzyme that, among other functions, removes acetyl groups from microtubules, improved axonal transport and neurodegeneration in models of neurodegenerative diseases such as ALS, Huntington’s and Parkinson’s." (PMID 35409291, 2022). "HDAC6 inhibitor treatment also increased microtubule-based intracellular transport in motor neurons and fibroblasts derived from patients with amyotrophic lateral sclerosis (ALS) and in Drosophila models of Parkinson’s disease concurrent with improved motor function." (PMID 32638097, 2021).
viral infection (26 papers, 2015 to 2025). "We also investigated the possible mechanisms underlying the modulating ability of HDAC6 on viral infection in pig cells." (PMID 39861880, 2025). "Conversely, HDAC6 deficiency can limit viral infection by increasing DNA damage-mediated type I IFN production." (PMID 39861880, 2025). "To conclude, we highlight new studies that show HDAC6’s multi-functionality in protein structure, viral infection, innate immune response, upstream signaling, and the application of HDAC6 inhibitors in associated diseases." (PMID 37638049, 2023). "Previous studies showed that HDAC6 is implicated in virus infection, for example, HIV-1 fusion and infection were inhibited by HDAC6-mediated acetylation of α-tubulin, and HDAC6 inhibited influenza A virus replication." (PMID 36951571, 2023). "Recent evidence on HDAC6 function underlines its role as a key protein in the innate immune response to viral infection." (PMID 29281743, 2017). "Many previous reports have highlighted the role of HDAC6 in linking DNA damage response and viral infection." (PMID 39861880, 2025). "The complex effect of HDAC6 highlights its diverse functions in regulating viral infection under different circumstances." (PMID 39861880, 2025). "To investigate the species-specific HDAC6 effect on viral infection, we investigated how HDAC6 affects pseudorabies virus (PRV) and vesicular stomatitis virus (VSV) infection in pig cells using HDAC6 gene knockout (KO) and overexpression methods." (PMID 39861880, 2025). "Under basal conditions, wild-type STING showed modest IFN-β induction capacity, but progressive HDAC6 overexpression following viral infection led to dose-dependent suppression of IFN signaling." (PMID 41135681, 2025). "Since viral infection inhibited HDAC6 expression, high titers of virus can be more robust in reducing HDAC6 expression." (PMID 39861880, 2025). "On the contrary, HDAC6 KO inhibits viral infection by promoting DNA damage-mediated type I IFN secretion." (PMID 39861880, 2025). "Here, we investigated the role of HDAC6 in influencing viral infection in pig cells with the aim of exploiting the potential antiviral gene targets in pigs." (PMID 39861880, 2025). "The involvement in viral infections (see Section 4.1.3) indicates HDAC6 as another potential weapon to prevent and/or treat viral diseases." (PMID 39595195, 2024). "In parallel, the prominent affinity for ubiquitin residues makes HDAC6 capable of regulating viral infections, especially of influenza A (IAV), human immunodeficiency 1 (HIV-1), and Coxsackie A16 viruses (CA16)." (PMID 39595195, 2024). "This review summarizes the function of HDAC6 in viral infection, host antiviral immunity and immune-related disorders." (PMID 37638049, 2023). "HDAC6 is involved in the process of a range of viral infections and can be exploited as a potential therapeutic target for many disorders." (PMID 37638049, 2023). "It has been reported that HDAC6 inhibitors regulate viral infection, tumorigenesis and disease development." (PMID 37638049, 2023). "The results of the experiments with HDAC6 knockout mice highlight the effect of HDAC6 deletion on the immune system, confirming the importance of HDAC6 in viral infection." (PMID 37638049, 2023). "Recent research on HDAC6 activity emphasizes its importance in the innate immune response to viral infection." (PMID 37638049, 2023). "Inhibiting HDCA6 deacetylase activity drastically reduced rabies virus RNA synthesis, indicating that HDAC6 plays an essential role in viral infection." (PMID 37638049, 2023). "We thus tested the effects of different HDAC inhibitors, with a focus on a selective HDAC6 inhibitor, on immune and epithelial cells in in vitro models that mimic cells activation after viral infection." (PMID 35592335, 2022). "HDAC6 overexpression in cells and in transgenic mice enhances resistance to viral infection with the human acquired immunodeficiency virus (HIV-1), influenza A virus, and vesicular stomatitis virus." (PMID 31374992, 2019).
viral infection (continued). "In late stages of virus infection, HDAC6 plays an opposite role in virus release by inhibiting viral components trafficking to the cell membrane." (PMID 30518648, 2019). "HDAC6 is involved in immune synapse formation, misfolded-protein degradation, stress response, and virus infection." (PMID 30518648, 2019). "The immunoprecipitation result showed that HDAC6 can interact with IAV RNA polymerase components upon virus infection." (PMID 30518648, 2019). "HDAC6 has been reported to involve many important biological processes, including cell migration, immune response, viral infection, and the degradation of misfolded proteins." (PMID 28673326, 2017). "HDAC6 is a predominant deacetylase of microtubules and has been reported to play critical roles in viral infection." (PMID 28491824, 2017). "HDAC6 has been reported to modulate many important biological processes, including cell migration, immune responses, viral infections, and the degradation of misfolded proteins." (PMID 28673326, 2017). "With respect to HIV, the overexpression of HDAC6 reduces viral infection and decreases virus–cell membrane fusion by reducing Actub levels." (PMID 28052127, 2017). "Therefore, our results contribute novel insights into the implications of CoV infections and the role of HDAC6 in viral infection, thereby informing future therapeutic strategies aimed at mitigating the effects of CoVs on cellular function." (PMID 40938964, 2025). "This work demonstrates that HDAC6 could be a potential gene target for modulating viral infection in pigs." (PMID 39861880, 2025). "Thus, HDAC6 serves not only as a viral target but also as a regulator of the viral infection process." (PMID 40938964, 2025). "We guess that viral infection at moi = 1 may be more robust in compromising overexpressed HDAC6 compared to viral infection at moi = 0.1, thus limiting the IFN-regulatory effect of HDAC6 overexpression." (PMID 39861880, 2025). "In addition, the changes in HDAC6 expression upon viral infection have been reported to be different." (PMID 39861880, 2025). "HDAC6 plays a dual role in viral infection and pathogenesis." (PMID 39861880, 2025). "We started by studying how HDAC6 responds to viral infection in pig cells." (PMID 39861880, 2025). "HDAC6 is an acetylation eraser that plays a key role in viral infection and innate immunity." (PMID 39861880, 2025). "The present work investigates the role of HDAC6 in viral infection in pig cells." (PMID 39861880, 2025). "HDAC6 is a major regulator of the innate response against viral infections." (PMID 36951571, 2023). "In conclusion, these findings imply that enhancing HDAC6 responses may protect against viral infection and effectively demonstrate that HDAC6 may improve the host IFN-I response to obstruct viral pathogenesis." (PMID 37638049, 2023). "Moreover, HDAC6 can restrict many virus infections, for example, HDAC6 can inhibit influenza A virus replication, and HIV-1 fusion and infection can be inhibited by HDAC6-mediated deacetylation of tubulin." (PMID 36951571, 2023). "HDAC6 can also control viral infection by modifying the human immune system and autophagy." (PMID 37638049, 2023). "An overview of the effects of HDAC6 on viral infection and its substrates." (PMID 37638049, 2023). "Our data indicate that HDAC6 could inhibit TBK1 activity during dsRNA viral infection to suppress type 1 interferon (IFN) responses." (PMID 32849638, 2020). "The interplay between HIV-1 Nef and cellular HDAC6 may determine viral infection and pathogenesis, representing both molecules as key targets to battling HIV." (PMID 31736889, 2019). "Hdac6 is reported to interact with Runx2 as well as being involved in multiple cellular processes, including organization of the immune synapse, cell migration, protein degradation, and viral infections." (PMID 31815961, 2019). "Therefore, only full-length functional Nef is able to target HDAC6 to restore viral production rates and viral infection capacities." (PMID 31736889, 2019).
viral infection (continued). "Understanding the molecular mechanisms of HDAC6 at various periods of viral infection may illuminate novel strategies for developing antiviral drugs." (PMID 30518648, 2019). "Therefore, HDAC6 represents a new antiviral factor capable of determining viral infection and disease progression in HIV+ individuals." (PMID 31736889, 2019). "Moreover, most of these studies have shown that HDAC6 overexpression enhances resistance to viral infection in cells and in TG mice." (PMID 28052127, 2017). "Finally, our research on the role of TDP-43 in HIV-1 infection indicated that enhancing the HDAC6-associated autophagic degradative pathway through TDP-43 regulation could be decisive against HIV-1 infection, thereby impairing viral infection and spreading." (PMID 37108826, 2023). "Our data suggest that HDAC6 could modulate Akt activation in macrophages during viral infection." (PMID 32849638, 2020). "Mechanistic work showed that HDAC6 attenuates the DNA damage response to reduce host type I IFN secretion, thereby promoting viral infection." (PMID 39861880, 2025). "As the DNA damage inhibitor, HDAC6 reduced the viral infection-mediated DNA damage response, thereby reducing type I IFN secretion to facilitate viral infection." (PMID 39861880, 2025). "HDAC6 overexpression attenuated DNA damage levels, which can further reduce type I IFN production to promote viral infection." (PMID 39861880, 2025). "Human histone deacetylase 6 (HDAC6) not only inhibits this early HIV-1 Env/CD4-mediated signalling, but also viral infection and replication, in a deacetylase-dependent manner." (PMID 26105074, 2015). "Meanwhile, HDAC6 expression was not significantly altered during viral infection in vitro, and remained constant in the HSE mouse model." (PMID 39747662, 2025). "This work demonstrates that HDAC6 affects the infection process of multiple viruses by modulating type I IFN production, highlighting a regulatory role of HDAC6 linking host immune response and viral infection levels in pig cells." (PMID 39861880, 2025). "Likewise, HDAC6i or HDAC6 KO, as DNA damage inducers, strengthen the type I IFN response, ultimately limiting viral infection." (PMID 39861880, 2025). "In addition, the HDAC6 ∆NLS mutant apparently reduced the binding of cGAS to viral DNA and promoted viral infection." (PMID 39747662, 2025). "Furthermore, HDAC6 deletion suppressed poly (I:C)-induced Akt activation, as evidenced by decreased phosphorylation of Akt at Ser473 near the carboxy terminus, implies that HDAC6 might control the degree to which macrophages activate Akt during viral infection." (PMID 37638049, 2023). "It is evident that vEnv treatment led to downregulation of cellular HDAC10 and HDAC6 expression, and downregulation of HDAC10 by shRNA knock-down significantly enhanced HIV viral infection and/or replication, especially through facilitation of progeny virion infectivity." (PMID 28842659, 2017). "On the other hand, HDAC6 is unique among the classical HDAC family in being a cytoplasmic enzyme that regulates several important biological processes, including cell migration, immune synapse formation, viral infection, and misfolded protein degradation." (PMID 28767685, 2017). "Even though the role of HDAC6 in ASFV cytoplasmic factories formation is still to be proven, our findings on class I HDACs raise the possibility of using HDAC I inhibitors to disrupt ASFV infection, as demonstrated in other viral infections." (PMID 26389938, 2015). "Since HDAC6 expression level is directly related with the infectivity of both DNA and RNA virus, treatment with small molecular drugs regulating HDAC expression level could be exploited as the simple strategy to control virus infection." (PMID 39861880, 2025).
viral infection (continued). "This event may have negative consequences in HIV-1 LTNP-EC individuals, particularly if a negative regulation of TDP-43 occurs with a concomitant decrease in HDAC6 that renders cells more permissive against inefficient LTNP-EC Envs, thereby favoring viral infection." (PMID 35682862, 2022). "Histone deacetylase 6 (HDAC6) is a member of the HDAC family II that primarily catalyzes the deacetylation of cytoplasmic nonhistone proteins, thus playing a critical role in viral infection and antiviral immune response." (PMID 39747662, 2025).